NCAPG (non-SMC condensin I complex subunit G)
Description:
Regulatory subunit of the condensin complex, a complex required for conversion of interphase chromatin into mitotic-like condense chromosomes. The condensin complex probably introduces positive supercoils into relaxed DNA in the presence of type I topoisomerases and converts nicked DNA into positive knotted forms in the presence of type II topoisomerases.
Synonyms: hCAP-G; CAPG; FLJ12450; CAP-G; YCG1; CHCG; NY-MEL-3
Tractability: PROTAC: ubiquitination databases record sites on it.
Gene: Protein-coding gene on chromosome 4 (17,810,844 to 17,844,865, forward strand). Ensembl gene ENSG00000109805.
Subcellular location: Nucleus; Cytoplasm; Chromosome
Pathways (Reactome):
Cell Cycle: Condensation of Prometaphase Chromosomes
Gene Ontology:
Molecular function: protein binding
Biological process: mitotic chromosome condensation; positive regulation of chromosome condensation; positive regulation of chromosome segregation; positive regulation of chromosome separation
Cellular component: condensin complex; membrane; condensed chromosome; cytoplasm; cytosol; nucleus; chromosome; condensed chromosome, centromeric region; condensed nuclear chromosome
Genetic constraint (gnomAD): Loss-of-function variants: 40 observed, 77.62 expected, observed/expected ratio (o/e) 0.52, 90% interval 0.4 to 0.67. The upper end of that interval is the gene's LOEUF score, 0.67, which puts it in group 2 of 6, group 1 being the genes least tolerant of losing a copy. Missense variants: 870 observed, 990.09 expected, observed/expected ratio (o/e) 0.88, 90% interval 0.83 to 0.93. Synonymous variants: 310 observed, 351.27 expected, observed/expected ratio (o/e) 0.88, 90% interval 0.8 to 0.97.
Homologues: Orthologues: chimpanzee NCAPG (99% identical), macaque NCAPG (97% identical), rabbit NCAPG (90% identical), pig NCAPG (89% identical), dog NCAPG (86% identical), rat Ncapg (83% identical), guinea pig NCAPG (83% identical), mouse Ncapg (82% identical), tropical clawed frog ncapg (61% identical), zebrafish ncapg (51% identical), Drosophila melanogaster Cap-G (24% identical).
Diseases named in the same sentence as NCAPG in open-access papers:
NCAPG is named in the same sentence as 77 diseases in open-access papers, as found by Europe PMC text mining. Sharing a sentence is not in itself a finding about the gene and the disease. The quoted sentences say what the papers report.
hepatocellular carcinoma (34 papers, 2018 to 2024). A malignant tumor that arises from hepatocytes. "Importantly, high NCAPG level was significantly associated with unfavorable survival in various cancer types such as hepatocellular carcinoma (HCC), breast, lung or ovarian cancer." (PMID 32300299, 2020). "The oncogenic role of NCAPG has been identified in several tumours, including prostate cancer, breast cancer, gliomas, gastric cancer and hepatocellular carcinoma." (PMID 39046429, 2024). "For example, NCAPG is overexpressed in hepatocellular carcinoma and glioma but underexpressed in out-of-niche primary tumor cells of multiple myeloma and acute myeloid leukemia." (PMID 36996493, 2023). "As for NCAPG, it has been proved to be involved in the development of prostate cancer, lung adenocarcinoma, hepatocellular carcinoma, and non-small cell lung cancer." (PMID 37192046, 2023). "In hepatocellular carcinoma, Ai J suggested that microRNA-181c inhibited growth and metastasis by targeting NCAPG." (PMID 35254214, 2022). "A recent study showed that overexpression of NCAPG promoted cell proliferation and decreased cell apoptosis in hepatocellular carcinoma via activating PI3K-AKT signaling pathway." (PMID 36258196, 2022). "Current studies have demonstrated that NCAPG was involved in the pathogenesis of a variety of malignant tumors, such as hepatocellular carcinoma, renal cell carcinoma, breast cancer, and prostate cancer." (PMID 35986371, 2022). "Recent studies have reported abnormal expression of NCAPG in gastric cancer, lung adenocarcinoma, prostate cancer, breast cancer, and hepatocellular carcinoma." (PMID 36233060, 2022). "In our previous study, we found that microRNA-181c can suppress the growth and metastasis of hepatocellular carcinoma by modulating NCAPG expression." (PMID 35864529, 2022). "Our transcriptome sequencing results indicated that the PI3K-AKT pathway plays an important role in the mechanism by which NCAPG enhances the proliferation of hepatocellular carcinoma." (PMID 35864529, 2022). "In hepatocellular carcinoma, Wang verifies that depletion of NCAPG contributes to hepatocellular carcinoma cell cycle arrest at the S phase and induces apoptosis." (PMID 33927744, 2021). "For example, NCAPG exerted oncogenic functions in hepatocellular carcinoma via regulating PI3K/AKT signaling." (PMID 35211508, 2021). "To date, previous study shows the involvement of NCAPG in hepatocellular carcinoma and breast, lung, and ovarian cancers." (PMID 33927744, 2021). "In another work, silencing NCAPG in hepatocellular carcinoma cells inhibited proliferation and induced apoptosis." (PMID 32070024, 2020). "Furthermore, CCNB2, MAD2L1, BUB1, and NCAPG are significantly upregulated in hepatocellular carcinoma (HCC) tissues and are implicated in the growth and metastasis of HCC cells." (PMID 32265985, 2020). "NCAPG has been reported to be a mitotic gene, and its overexpression is responsible for the cell proliferation and migration in hepatocellular carcinoma." (PMID 30390708, 2018). "Knockdown of NCAPG significantly reduced the viability of hepatocellular carcinoma cells by regulating Bax, cleaved caspase-3, E-cadherin, N-cadherin, cyclin A1, CDK2, and Bcl-2, and the expression of HOXB9 induces apoptosis and cell cycle arrest in the DNA synthesis phase." (PMID 36996493, 2023). "In human research, NCAPG could promote the proliferation of many types of cells, such as hepatocellular carcinoma cells, colorectal cancer cells, and pulmonary artery smooth muscle cells." (PMID 37893897, 2023). "Dysregulation of NCAPG may contribute to the progression of hepatocellular carcinoma and gastric cancer." (PMID 36176446, 2022). "Studies suggested that NCAPG might be an essential oncogene of hepatocellular carcinoma and gliomas by inducing apoptosis." (PMID 34268107, 2021). "NCAPG, an oncogene of HCC (hepatocellular carcinoma), promotes cell proliferation and inhibits cell apoptosis." (PMID 39545257, 2024).
hepatocellular carcinoma (continued). "NCAPG has been reported that to promote hepatocellular carcinoma (HCC) cell proliferation and migration and to be a potential biomarker of endometrial cancer progression and prognosis." (PMID 35280743, 2022). "And the high expression of NCAPG may play an essential role in tumorigenesis and progression, serving as a promising molecular target for cancer treatment and prognostic biomarkers for hepatocellular carcinoma (HCC)." (PMID 35677427, 2022). "We found that NCAPG overexpression was significantly correlated with positive lymph node metastasis in gastric cancer and NSCLC, TNM stage in hepatocellular carcinoma, age in glioma, differentiation in hepatocellular carcinoma and glioma, and vascular invasion in gastric cancer." (PMID 36996493, 2023). "NCAPG, non-SMC subunit in the concentrate I complex, might promote the proliferation of hepatocellular carcinoma (HCC), but the mechanism is unclear." (PMID 35864529, 2022).
prostate carcinoma (26 papers, 2018 to 2026). A carcinoma that arises from epithelial cells of the prostate gland. "Current researches showed that NCAPH up-regulated predicts a poor prognosis of prostate cancer patients and NCAPG promotes the progression of LUAD." (PMID 38172945, 2024). "Previous studies have shown that NCAPG is highly expressed in many malignant tumors, such as gastric cancer, liver cancer, glioma, and prostate cancer, and its expression level is closely related to the poor prognosis of the tumors." (PMID 35986371, 2022). "The results showed that the expression of NCAPG was upregulated in colorectal cancer, breast cancer, and prostate cancer while weak expression in lung cancer." (PMID 35601741, 2022). "Previous studies suggested that NCAPG was significantly up-regulated in a variety of malignant solid tumors including liver cancer, prostate cancer, gastric cancer, renal clear cell carcinoma, etc." (PMID 35254214, 2022). "Studies have shown that NCAPG is involved in the pathogenesis of a variety of cancers, including prostate cancer, paediatric glioma, renal cell carcinoma, multiple myeloma and melanoma." (PMID 35864529, 2022). "In recent years, there are more and more studies on the abnormal expression of NCAPG in prostate cancer, lung cancer, breast cancer, and other cancers." (PMID 32626756, 2020). "Recently, NCAPG were negatively regulated by miR-145-3p and miR-145-3p was downregulated in prostate cancer cells." (PMID 29467813, 2018). "And we further found that NCAPG displayed moderate cytoplasmic positivity, especially strongly staining in lymphoma, testicular, colorectal, and endometrial cancers while weakly stained in gliomas and prostate cancer." (PMID 35601741, 2022). "Moreover, up-regulated NCAPG expression is also linked to the cancer pathological stage of castration-resistant prostate cancer; knockdown of NCAPG inhibited cancer cell aggressiveness." (PMID 35211508, 2021). "In prostate cancer cells, a decrease in its expression promotes the expression of proliferation-related genes MELK, NCAPG, BUB1, and CDK1, thereby promoting cell proliferation." (PMID 41546098, 2026). "NCAPG shows increased migration and proliferation in HCC since it has high expression in HCC castration-resistant cancers of the prostate and melanoma." (PMID 39911278, 2025). "Previous research has demonstrated that poor prognosis is correlated to abnormal condensin complex I expression of the NCAPH, NCAPG, and NCAPD2 subunits in NSCLC, liver cancer, colorectal cancer, breast cancer, and prostate cancer." (PMID 38566039, 2024). "NCAPG is abundantly expressed in HCC, castration-resistant prostate cancer and melanoma and it was showed that NCAPG promotes HCC proliferation and migration." (PMID 32300299, 2020). "Our previous studies revealed that tumor-suppressive miR-145-3p was closely involved in human cancer pathogenesis by targeting oncogenes, for example, MTDH in LUSQ; MELK, NCAPG, BUB1, and CDK1 in prostate cancer; MYO1B in head and neck cancer; and MYO1B and DHRS2 in esophageal cancer." (PMID 31514295, 2019). "Studies also revealed that non-SMC condensin I complex subunit G (NCAPG) could be the downstream target of miR-99a-3p in prostate cancer cells, and distinctly influenced proliferation, migration and invasion." (PMID 35884594, 2022).
breast carcinoma (24 papers, 2014 to 2025). "Growing evidence has indicated that aberrant NCAPG expression is strongly associated with various cancers, such as liver, renal cell, prostate, and breast cancer." (PMID 35292013, 2022). "PTBP1 and NCAPG play a role in some cancers, including colorectal cancer, renal cell carcinoma, breast cancer, and glioma, and can regulate tumorigenesis, invasion, and migration." (PMID 41438761, 2025). "Later on, the expression of NCAPG was often closely associated with the survival outcome and clinical pathology of patients with diseases such as NSCLC, renal clear cell carcinoma, breast cancer, and gastric cancer." (PMID 36996493, 2023). "At the same time, in HER2-positive breast cancer, NCAPG promotes the development of trastuzumab resistance by activating the SRC/STAT3 axis." (PMID 35254214, 2022). "To further verify the results, we extracted the differential expression of NCAPG in several common cancers from online database, including colorectal cancer, breast cancer, and lung cancer." (PMID 35601741, 2022). "Multiple studies have mentioned that NCAPG was highly expressed in a variety of solid tumors including liver cancer and breast cancer." (PMID 35254214, 2022). "Statistical results of 35 pairs of breast cancer tissue microarray staining showed that NCAPG was upregulated in tumor tissues." (PMID 32300299, 2020). "To verify the expression of NCAPG in tumors, we extracted mRNA from 12 pairs of breast cancer and the normal tissue adjacent to the cancer to verify the expression of NCAPG." (PMID 32300299, 2020). "The qPCR results showed NCAPG was upregulated in breast cancer, which was consistent with analysis of TCGA data." (PMID 32300299, 2020). "NCAPG has been shown to be relevant in a number of different cancer types, including liver cancer, bladder cancer, renal cell carcinoma, multiple myeloma, melanoma and breast cancer." (PMID 35372056, 2022). "Since NCAPG has been proposed as therapeutic target to overcome trastuzumab resistance in breast cancer, our results indicate that NCAPG is not only an important oncogenic driver but may also serve as a new target for treating NSCLC." (PMID 35180865, 2022). "Furthermore, knockdown of NCAPG by siRNA significantly decreased cell proliferation in breast cancer cell line MDA-MB-231." (PMID 32300299, 2020). "To investigate whether high expression NCAPG plays a crucial role in breast cancer, we suppressed NCAPG expression by siRNAs in MDA-MB-231." (PMID 32300299, 2020). "Moreover, consistent with analysis of TCGA data, both the mRNA and protein levels of NCAPG were upregulated in breast cancer tissues compared with adjacent tissues." (PMID 32300299, 2020). "Moreover, knockdown of NCAPG can resensitize HER2-resistant breast cancer cells to trastuzumab, indicating that NCAPG has the potential to become a predictive biomarker and target for therapeutic intervention for trastuzumab resistance in HER2-resistant breast cancer cells." (PMID 36276152, 2022). "Additionally, we found that the protein of NCAPG was upregulated in breast cancer." (PMID 32300299, 2020). "Representative staining patterns of NCAPG expression in HCC, breast cancer, lung cancer, and ovarian cancer by IHC were shown from Human Protein Atlas." (PMID 32300299, 2020). "These functional analyses agree on the association of a few genes with breast cancer survival and prognosis, such as DLGAP5, NCAPG, and RRM2, which are not involved in 1CM." (PMID 39125744, 2024). "Moreover, NCAPG has been shown to modulate the SRC/STAT3 signaling pathway and confer resistance to trastuzumab in HER2-positive breast cancer cells." (PMID 35280743, 2022). "NCAPG has been reported as an oncogene in liver cancer, gastric cancer, breast cancer, and other tumours but has not yet been studied in CRC." (PMID 35155186, 2021).
breast carcinoma (continued). "The common relevant genes of NCAPG were analyzed based upon 3,091 tumor samples, including HCC (n=377), breast cancer (n=1,097), lung adenocarcinoma (n=522), lung squamous cell carcinoma (n=504), and ovarian cancer (n=591) expression profiling datasets, respectively." (PMID 32300299, 2020). "Moreover, high NCAPG level significantly correlated with poor survival in patients with several types of cancer, including HCC, breast cancer, lung cancer, and ovarian cancer." (PMID 32300299, 2020). "Furthermore, NCAPG was a prognostic marker in several types of tumor, including HCC, breast cancer, lung cancer, and ovarian cancer." (PMID 32300299, 2020).
glioma (18 papers, 2016 to 2026). A benign or malignant brain and spinal cord tumor that arises from glial cells (astrocytes, oligodendrocytes, ependymal cells). "Some studies have reported that NCAPG dysregulation is associated with cancers, including gliomas and melanomas." (PMID 36147508, 2022). "Collectively, these results showed that NCAPG was highly expressed in glioma cells and was significantly associated with glioma cell proliferation and migration." (PMID 35280743, 2022). "The present study was designed to determine the biological functions of NCAPG in glioma and to evaluate the association of NCAPG expression with glioma progression." (PMID 35280743, 2022). "The results also highlighted that, in glioma patients, the expression of NCAPG is associated with the tumor grade and that NCAPG expression increases significantly with the tumor grade." (PMID 35372056, 2022). "A heatmap was constructed showing the 50 most significant genes positively associated with NCAPG expression in glioma." (PMID 35280743, 2022). "Univariate logistic regression analysis confirmed the association between high NCAPG expression and poor clinicopathological characteristics in glioma patients." (PMID 35280743, 2022). "We found that NCAPG, a mitosis-associated chromosomal condensing protein, is highly expressed in glioma tissues." (PMID 35372056, 2022). "In conclusion, our results suggest that NCAPG expression is associated with malignant biological processes and can be used as a biomarker for glioma." (PMID 35372056, 2022). "Moreover, underlying evidence indicated that NCAPG regulates immune cell infiltration in the glioma tumor microenvironment." (PMID 35280743, 2022). "Cox proportional hazard model analysis confirmed that the numbers of B cells, CD8+ T cells, CD4+ T cells, macrophages, neutrophils, and dendritic cells infiltrating into gliomas, as well as NCAPG expression, were associated with a poorer prognosis in glioma patients." (PMID 35280743, 2022). "Wherein, NCAPG could be positively related to CDCA2 (cell division cycle-associated protein 2) in glioma, and the over-expression of NCAPG may regulate the cell cycle and promote the proliferation, migration, and invasion of glioma cells." (PMID 35992200, 2022). "Moreover, Cox proportional hazard analysis showed that populations of B cells, CD8+ T cells, CD4+ T cells, macrophages, neutrophils, and dendritic cells, along with NCAPG expression, were significantly associated with poor OS in glioma patients." (PMID 35280743, 2022). "NCAPG expression in glioma is likely to be key in diagnostic and treatment strategies for glioma." (PMID 35372056, 2022). "We discovered that NCAPG may serve as an independent risk factor in the TCGA-glioma dataset." (PMID 35372056, 2022). "In contrast, single-cell analysis based on the CancerSEA database revealed that PTBP1 and NCAPG are associated with various functions such as cell cycle, DNA damage, DNA repair, and proliferation, suggesting that they may be involved in the malignant progression of glioma." (PMID 41438761, 2025). "In this study, we identified hsa_circ_0069280, derived from NCAPG, as an oncogene that was overexpressed in glioma, promoting GSCs progression." (PMID 36635261, 2023). "In this study, we firstly confirmed that hsa_circ_0069280, which was derived from the NCAPG gene, was remarkably upregulated in glioma patients, especially in high grade gliomas." (PMID 36635261, 2023). "Knockdown of NCAPG in glioma cell lines, as verified by qRT-PCR assay, significantly reduced the proliferation of glioma cells." (PMID 35280743, 2022). "The knockdown of NCAPG significantly decreased cell proliferation, migration, and invasion ability of glioma cells." (PMID 35372056, 2022). "The association between NCAPG expression and glioma was evaluated immunohistochemically, using antibody to NCAPG to detect the protein level in glioma tissues." (PMID 35280743, 2022).